CDT1 (chromatin licensing and DNA replication factor 1)
Diseases named in the same sentence as CDT1 in open-access papers (continued):
Sharing a sentence is not in itself a finding about the gene and the disease.
cancer (continued). "CDT1 was found to be highly elevated in a variety of malignancies when compared to normal tissues, according to a pan-cancer analysis utilizing Wilcoxon rank-sum and Wilcoxon signed-rank tests (P < 0.001)." (PMID 37790630, 2023). "Herein, the specific relationship between PCGEM1/miR-129-5p/CDT1 in PCa was verified, and its effect on cancer cell biological function was discussed." (PMID 35412947, 2022). "Both CDT1 and Geminin are overexpressed in cancer cell lines as well as in several tumor types, even from the early stages of cancer progression." (PMID 35548337, 2022). "CDT1 has been considered to contribute to cell proliferation and genome instability and to be often misregulated in cancer." (PMID 35884419, 2022). "Deregulation of CDT1 has been shown to trigger a DNA damage response that contributes to genomic instability, and CDT1 has been reported to function as an oncogene in various human cancers." (PMID 36281462, 2022). "It was confirmed that Ki-67 and CDT1 colocalized in the same nucleus in the cancer cells and hepatocytes in lobule (3D view image)." (PMID 36443564, 2022). "It has been suggested that in some cancer cells, this protein plays an essential and unique role in initiating DNA replication by regulating the activity of cdt1." (PMID 32972865, 2022). "The merged images revealed colocalization of CDT1 and Ki-67, mainly in the nuclei of hepatocytes and cancer cells, representing 360° view movies of 3D reconstructed images of CDT1- and Ki-67-positive cells." (PMID 36443564, 2022). "Numerous studies published in the last few years have clarified CDT1's prognostic function in various types of cancer." (PMID 35173548, 2022). "Taken together, our results suggest that compound AF615 induces DNA damage and blocks DNA synthesis in cancer cell lines in a CDT1-dependent manner." (PMID 35548337, 2022). "CDT1 and Geminin are central regulators of licensing, while their aberrant protein expression has been reported in various cancer-derived cell lines, as well as in different human tumor specimens." (PMID 35548337, 2022). "CDT1 overexpression or Geminin depletion induces DNA re-replication and cell cycle arrest in S and G2 phase, especially in cancer cell lines." (PMID 35548337, 2022). "Previous studies have shown that, overexpression of CDT1, or knock-down of Geminin, leads to accumulation of double strand breaks, cell cycle arrest and apoptosis in cancer cell lines." (PMID 35548337, 2022). "We have provided evidence that treatment with compound AF615 leads to reduced interaction of CDT1 and Geminin both in-vitro and in cancer cells." (PMID 35548337, 2022). "We observed atypical hepatocytes and cancer cells that were positive for both Ki-67 and CDT1 by CLSM." (PMID 36443564, 2022). "Knock-down of CDT1 reduced the effect of compound AF615 in cancer cells, revealing that endogenous CDT1 is required for the mechanism of action of compound AF615." (PMID 35548337, 2022). "Overexpression of CDT1 or down–regulation of Geminin leads to DNA re-replication, double strand breaks and apoptosis in different cancer cell lines." (PMID 35548337, 2022). "Deregulation of Geminin and CDT1 proteins results in different responses in normal versus cancer cells." (PMID 35548337, 2022). "First, the transcriptional levels of CDT1 in various human cancers and their counterpart normal tissues were investigated in the TCGA and GTEx datasets." (PMID 34631549, 2021). "We first examined the transcriptional levels of CDT1 in different types of cancer using independent datasets from three different sources (ONCOMINE, TCGA, and GTEx)." (PMID 34631549, 2021). "MLN4924 can inhibit the activity of CRL4CDT2 ubiquitin ligase to stabilize CDT1 and trigger checkpoint activation, apoptosis, and senescence in cancer cells." (PMID 33557942, 2021). "Higher levels of CDT1 mRNA tended to be expressed in tissues obtained from HCC patients with advanced cancer stages (p < 0.01)." (PMID 34631549, 2021).
cancer (continued). "We examined CDT1 expression levels in different types of cancer using independent datasets from different sources." (PMID 34631549, 2021). "CDT1 overexpression in several human cancers reportedly leads to abnormal cell replication, activates DNA damage checkpoints, and predisposes malignant transformation." (PMID 34631549, 2021). "We then evaluated pan-carcinoma CDT1 expression levels using ONCOMINE, revealing the same expression trend as above." (PMID 34631549, 2021). "Our results demonstrated that both in vitro and in vivo, MLN4924 induces stabilization of replication initiation factor CDT1 resulting in DNA re-replication with >4N DNA content which has been observed in a few other cancer models." (PMID 32166000, 2020). "The overexpression of CDK1, TYMS, CDT1, and CCNA2 and the underexpression of PRKACB were associated with tumorigenesis, defective cell signaling, or aberrant metabolism in other cancers." (PMID 31205467, 2019). "As essential for proper genome replication, CDT1 is considered to play an important role in mediating DTL induced cancer cell proliferation." (PMID 31409387, 2019). "The anticipatory Cdt1 accumulation to promote MCM loading in G1 was originally proposed from experiments in cancer-derived cell lines." (PMID 29148972, 2017). "Patients whose tumors expressed either Cdc6 or Cdt1 at a high level also had a shorter survival time compared to those whose cancer expressed both Cdc6 and Cdt1 at a low level (Wilcoxon-Gehan test, p = 0.052)." (PMID 28428557, 2017). "So far, upregulation of Cdt1 has been found in many cancers such as colon and non-small-cell lung cancer." (PMID 26460955, 2015). "DNA damage dictated DTL to downregulate CDT1, failure of which led to genomic instability and cancer." (PMID 25186767, 2014). "In conclusion, these data demonstrate that CDT2 is indispensable for CDT1 degradation in response to DNA damage only in cancer cells." (PMID 25115388, 2014). "This implies that in normal cells CRL4CDT2 is dispensable and one or more alternate mechanisms of CDT1 degradation were actively functioning while in cancer cells CRL4CDT2 is indispensable." (PMID 25115388, 2014). "We show here that cell death, rereplication and CDT1 accumulation after CDT2 depletion occurred exclusively in cancer cells." (PMID 25115388, 2014). "In rapidly proliferating cells such as cleavage stage embryos, pre-implantation embryos and cancer cells, Cdt1 activity is the rate-limiting factor for the origin licensing." (PMID 24069236, 2013). "CDT1 is a potential oncogene, highly expressed in cancer cell lines CaSki, HeLa, LNcap, MCF7, MDAMB231, and Saos." (PMID 23194200, 2012). "In conclusion, our study suggests that genotoxic therapies used routinely against cancer differentially affect Cdt1-dependent degradation and consequently licensing regulation." (PMID 22479651, 2012). "Supported by the observation that Cdt1 is overexpressed in human cancer cells, it has been suggested that DNA re-replication can lead to the chromosomal instability and malignant transformation." (PMID 19390600, 2009). "Cdt1 transcription is driven by E2F transcription factor, which is often deregulated in cancer cells, for example by RB pathway disturbance." (PMID 17042960, 2006). "Using a gene effect score of <−1 as a threshold for dependency, CDT1 loss was not tolerated across most cancer cell lines whereas the consequences of CDC6 and DBF4 loss were less broad across the panel." (PMID 40460119, 2025). "Interestingly, both the overexpression of CDT1 and the removal of geminin lead to genome instability and cancer, indicating that it is essential for DNA replication control to keep CDT1 protein levels in check." (PMID 41365879, 2025).
cancer (continued). "Notably, CDC6 and CDT1 showed lower gDS and PubTator scores, are referred to as Tbio in Target development levels, and positively correlated with cancer-related pathways, which is worthy of further experimental exploration in RCC." (PMID 38728235, 2024). "CDC6 and CDT1, for instance, positively correlated with various cycle- and proliferation-related pathways, such as E2F targets and G2M checkpoint, indicating that they regulate cancer development by activating these pathways." (PMID 38728235, 2024). "In addition, CDT1 overexpression alone can induce overt re-replication in some cancer-derived cells." (PMID 37790630, 2023). "Conversely, in cancers, Cdt1-mediated re-replication might occur unevenly, where early-replicating origins, but not late-replicating origins, preferentially re-fire again within the same S phase, which could lead to genome instability." (PMID 37760529, 2023). "This phenotype is consistent with the cellular effects evident upon origin re-licensing and re-replication in cancer cells, underlying that compound AF615 may have a similar effect by deregulating the complex CDT1/Geminin." (PMID 35548337, 2022). "Since compound AF615 phenocopies the cellular effects induced by abnormal CDT1 and/or Geminin expression, we examined whether it affects the proliferation of cancer cells." (PMID 35548337, 2022). "Since compound AF615 affected differently the cell cycle progression of cancer and normal cells, we hypothesized that this phenotype may be related to the expression levels of CDT1 and Geminin." (PMID 35548337, 2022). "A second explanation could be that cancer cells harbor abnormal protein ratios of CDT1 and Geminin, in which a partial inhibition of Geminin may be sufficient to induce activation of the DNA damage response and cell cycle arrest." (PMID 35548337, 2022). "CDT1 and Ki-67 were colocalized in the nuclei of both hepatocytes and cancer cells." (PMID 36443564, 2022). "Moreover, compound AF615 induces DNA damage, inhibits DNA synthesis and reduces viability selectively in cancer cell lines, and this effect is CDT1-dependent." (PMID 35548337, 2022). "Therefore, we utilized the TCGA data to compare transcriptional levels of CDT1 between HCC cancer samples and normal samples." (PMID 34631549, 2021). "Further, overexpression of CDT1 and MCMs has been previously reported in several human cancers." (PMID 34631549, 2021). "The hub protein CDT1 is associated with genotoxic stress, which results in aberrant cell proliferation leading to cancer formation, but its association with the CMP is not known." (PMID 32196466, 2020). "It is reported DTL depletion in cancer cells caused apoptotic death of cancer cells associated with rereplication due to the loss of CDT1 degradation, but not in non-transformed cells." (PMID 31409387, 2019). "It has been reported that CDT1 function as an oncogene in several types of human cancers." (PMID 28969065, 2017). "Preferential sensitivity of some cancer cells to Gmnn depletion may involve their overexpression of pre-RC proteins including Cdt1 and Cdc6, which stimulate pre-RC complex re-assembly and re-firing of origins of replication within the same cell cycle." (PMID 29234490, 2017). "Additionally, Cdt1 overexpression drives oncogenic transformation in cell culture and tumor formation in mouse models and is observed in various human cancer cell lines." (PMID 27898391, 2016). "In fact, many cancer-derived cell lines exhibit higher-than-normal expression of Cdt1." (PMID 28025526, 2016). "And Cdt1 overexpression could play a role in cancer development because its high level can occur early in premalignant diseases and participates in tumor development." (PMID 26460955, 2015). "Cdt1 is an oncogene overexpressed in several human cancers and cancer cell lines." (PMID 24423875, 2014).
cancer (continued). "It will be interesting to determine if TLS function or DNA repair is affected in cancer cells overexpressing Cdt1, or other degrons, and if this may alter the sensitivity of cancer cells to specific chemotherapy." (PMID 24423875, 2014). "Thus, inhibiting the NAE by MLN4924 prevents destruction of numerous substrates of the CRLs, involved in cell proliferation and cancer pathways, such as not only CDT1 and p21, but also cyclins and checkpoint kinases." (PMID 25115388, 2014). "We conclude that cisplatin and MMS lead to proteolysis of Cdt1 in different cancer cells." (PMID 22479651, 2012). "Thus, mitosis-specific DNA damage-inducing reagents would be useful chemotherapeutic drugs for cancer cell treatment by degrading Cdt1 and thus inhibiting replication licensing." (PMID 23029527, 2012). "Here we explore the effects of anticancer agents with distinct mechanisms of action on the targeting of the replication factor Cdt1 in different human cancerous cell lines, simulating the effect of these drugs in the activation of Cdt1-dependent checkpoint in different cancer types." (PMID 22479651, 2012). "Since Cdt1 is overexpressed in cancer cells, this could be a new molecular mechanism leading to carcinogenesis." (PMID 17042960, 2006). "The induced chromosomal instability may eventually lead to carcinogenesis and Cdt1 overexpression is in fact often observed in human cancers." (PMID 17042960, 2006). "However, it should be noted that cancer cells have been used in most of the reported studies and geminin has roles other than in Cdt1 inhibition, for example in transcriptional regulation." (PMID 17042960, 2006). "Indeed, it is reported that overexpression of Cdt1 can induce overt re-replication in cancer-derived cell lines, with activation of ATM/ATR checkpoint pathways." (PMID 17042960, 2006). "The fact that Cdt1-induced re-replication has been observed in cancer-derived cell lines could provide an answer." (PMID 17042960, 2006). "By applying an AlphaScreenTM HTS assay, we discovered a small molecule inhibitor of CDT1/Geminin protein complex, which facilitates effective targeting of cancer cells, thereby providing a promising lead compound that could serve as a chemical scaffold for further chemical optimization." (PMID 35548337, 2022). "Given that CDT1 is involved in the formation of the pre-replication complex that is necessary for DNA replication, we assumed that this gene may be upregulated in atypical and cancer cells which includes active cell cycles." (PMID 36443564, 2022). "Thus, the fact that Ki-67 and CDT1 colocalize in some hepatocytes and cancer cells nuclei suggests that CDT1 may be involved in active cell proliferation." (PMID 36443564, 2022). "Therefore, considering the heterogeneous localization of CDT1 in lobules, we will determine the presence and degree of genetic abnormalities and instability in various hepatocytes or cancer cells within lobules by applying novel spatial transcriptomics technology for visualization using FFPE tissue." (PMID 36443564, 2022). "Accumulated literature suggests that CDT1 may be a new marker for cancer diagnosis and prognosis." (PMID 35412947, 2022). "Furthermore, CDT1 expression is downregulated in human tumor specimens, so it may represent a novel marker useful for cancer diagnosis and prognosis." (PMID 33591950, 2021). "However, the role of Cdc6 and Cdt1 in cancer development is less well understood." (PMID 28428557, 2017). "However, the effect of altering the GMNN/CDT1 balance in tumourigenic cells (which express higher levels of these genes compared to normal cells) is unclear as there is debate about how the GMNN/CDT1 balance influences the development and progression of cancer." (PMID 25372501, 2014). "Moreover, Cdt1 is overexpressed in different cancers while recent findings suggest that its expression may participate in the development of the malignant phenotype." (PMID 22479651, 2012).
cancer (continued). "Since several different genetic alterations, each of which leads to excess activity of the initiation proteins Cdt1 and/or Cdc6, can induce re-replication in mammalian cells, it is likely that induction of re-replication is one of the genome-destabilizing processes that can lead to cancer." (PMID 18154680, 2007). "Importantly, Cdt1 protein is actually overexpressed in human cancer cells." (PMID 17042960, 2006). "However, at d14 we observed an increase in geminin+ cells, a decrease in CDT1+ cells and an increase in the percentage of non‐senescent cells within the sorted senescent population, suggesting that senescent cancer cells may have escaped their senescent state and re‐entered the cell cycle." (PMID 41159617, 2025). "USP37 regulates replication stress by stabilizing CDT1 and CHK1, but these findings must be validated for different cancers." (PMID 34758854, 2021). "Specifically, EGFR is a widely studied oncogene with a potential role in cancer therapeutics, six are core genes (AURKA, CDK1, CDT1, PRKDC, RAD51, and XRCC2), six are potential drug targets, and five were identified as drug actionable genes." (PMID 33240468, 2020). "Searching for other proliferation genes resulted in finding EXO1, MCM10, GINS2, CDT1, ORC6L, and BLM had the same pattern indicating they are most likely necessarily highly transcribed in cancer." (PMID 31857847, 2019). "As all cancer cell lines underwent rereplication after CDT2 depletion, we inferred that the stability of the licencing factor CDT1 was affected." (PMID 25115388, 2014). "This was indeed the case, as the list of genes exclusively detected in cancer, including TRAF7, PRPS1, CDT1, and ZWINT, were previously reported as cancer marker genes." (PMID 20454660, 2010). "CDT1 overexpression does not induce any detectable DNA re-replication in non-transformed cells, in contrast to cancer cells which are driven to apoptosis." (PMID 35548337, 2022). "We examined differences in ΔCt value of CDT1 among the three population in nonatypical hepatocytes, atypical hepatocytes and cancer cells in the same FFPE sections in different cell populations in Cohort 5 by LCM." (PMID 36443564, 2022). "Because massive re-replication can drive cell death specifically in checkpoint-compromised cancer cells, both CDT1 stabilization by inactivation of ubiquitin-mediated degradation and inhibition of DOT1L are currently being explored as novel anti-cancer therapeutic strategies." (PMID 34103496, 2021). "As the result, DNA replication licensing proteins CDT1 and ORC1, two well-known CRL/SCF substrates, accumulate to trigger DNA damage response, leading to G2–M cell cycle arrest, senescence and/or apoptosis in cancer cells." (PMID 32264924, 2020). "Consequently, CDT1 inhibits cell proliferation and displays an important effect on MLN4924 anti-cancer activity." (PMID 32166000, 2020). "Conversely, CDT2 silencing abrogated the CDDP induced degradation of CDT1 in cancer cells, while it did not affect CDT1 degradation in non-transformed cells." (PMID 25115388, 2014). "As expected, cell treatment with the DNA damaging agent cisplatin (CDDP) resulted in CDT1 degradation in both cancer and non-transformed cells transfected with control siRNAs." (PMID 25115388, 2014). "This possibility is consistent with the observation that overexpression of Cdt1 and Cdc6, or a non-degradable form of Cdt1 alone can trigger rereplication in cancer cells though additional work is necessary to confirm this model." (PMID 17319958, 2007). "Cancer cells constitutively overexpress replication initiation factors such as ORC1, CDC6, Cdt1, and MCM, so that ORC1 degradation in S phase may be insufficient to fully suppress its function." (PMID 17042960, 2006).